RNU6-869P (RNA, U6 small nuclear 869, pseudogene)
Gene: Small nuclear RNA gene on chromosome 8 (126,504,763 to 126,504,869, forward strand). Ensembl gene ENSG00000207138.
Homologues: Orthologues: chimpanzee U6 (99% identical), macaque U6 (94% identical), rabbit U6 (90% identical), guinea pig U6 (81% identical). Paralogues in human: RNU6-12P (93% identical), RNU6-13P (93% identical), RNU6-16P (93% identical), RNU6-32P (93% identical), RNU6-36P (93% identical), RNU6-1 (93% identical), RNU6-17P (93% identical), RNU6-18P (93% identical), RNU6-2 (93% identical), RNU6-20P (93% identical), RNU6-3P (93% identical), RNU6-45P (93% identical), and 1286 more.